P2RY14 (purinergic receptor P2Y14)
Diseases named in the same sentence as P2RY14 in open-access papers (continued):
Sharing a sentence is not in itself a finding about the gene and the disease.
tumor (13 papers, 2018 to 2026). "Nevertheless, the underlying mechanism by which P2RY14 regulates tumor growth remains unclear." (PMID 39440060, 2024). "In vivo, P2ry14 knockout increased mouse survival, decreased SC proliferation, improved nerve Remak bundle morphology, and decreased tumor initiation." (PMID 35311647, 2022). "We performed gene expression analysis on these cells and found that P2ry14 mRNA is elevated in p75+/EGFR+ SCP-like tumor-initiating cells." (PMID 35311647, 2022). "CCR8 and P2RY14 were differentially expressed in tumor tissues than normal tissues, and the results were validated at the protein level by immunohistochemistry experiments." (PMID 33692955, 2021). "Among them, there were significant differences in the expression of CCR8 and P2RY14 in tumor tissues and normal tissues." (PMID 33692955, 2021). "In particular, the expression of P2RY14 was reduced along with the progression of clinical stages and tumor size." (PMID 34306014, 2021). "On the other hand, this data suggests that P2RY14 play an important role in the regulation of the tumor immune microenvironment." (PMID 34306014, 2021). "Immunohistochemical staining results suggested that P2RY14 was mainly expressed in tumor stroma tissue." (PMID 34306014, 2021). "Briefly, low immune scores were associated with unfavorable prognosis and clinical-stage, larger tumor size, and the down-regulation of P2RY14 in HNSC patients." (PMID 34306014, 2021). "Similar to the results we obtained in TCGA-HNSC data set, the higher the expression of P2RY14 in the tumor tissue, the better the prognosis of the patient." (PMID 33692955, 2021). "The expression of CCR8 was significantly increased in tumor tissues (P<0.001), while the expression of P2RY14 was significantly decreased (P<0.001)." (PMID 33692955, 2021). "CIBERSORT algorithm was applied to analyze the proportion of tumor-infiltrating immune subsets and to further confirm the correlation of P2RY14 expression with the immune microenvironment." (PMID 34306014, 2021). "Both CCR8 and P2RY14 gene expression was significantly correlated with pathological tumor stage, T-stage, and gender (P<0.05)." (PMID 33692955, 2021). "Moreover, the investigation of protein expression levels of GDF6 and P2RY14 in OV and non-tumor tissues was conducted through the utilization of immune histochemistry (IHC) on the tissue microarray." (PMID 39440060, 2024). "In addition, P2RY14 expression was also found in different cancers suggesting P2RY14 as potential biomarker for specific neoplasms." (PMID 37250906, 2023). "To test if P2ry14 signaling might also play roles in tumor maintenance, we took pharmacological approaches." (PMID 35311647, 2022). "Interestingly, the expression levels of CCR8 and P2RY14 in tumor tissues were significantly correlated with gender, with women showing significantly higher levels of gene expression than men." (PMID 33692955, 2021). "The decreased expression of P2RY14 was significantly associated with advanced clinicopathological characteristics (clinical stage and tumor size) and poor prognosis, thus suggesting that P2RY14 might be a potential prognostic marker for HNSC." (PMID 34306014, 2021). "During the analysis of tumor-infiltrating immune subsets using the CIBERSORT algorithm, eight TICs were positively or negatively correlated with P2RY14 expression." (PMID 34306014, 2021). "P2RY14 has shown to be correlated with the survival, classification of TNM stages, and tumor-infiltrating immune cells (TICs) in HNSC patients." (PMID 34306014, 2021). "Quantification of the other subtypes confirmed that P2RY2, P2RY4 and P2RY14 were not significantly upregulated in the tumor samples compared to normal samples." (PMID 38773214, 2024). "Furthermore, we validated through IHC experiments that the expression of P2RY14 and GDF6 was decreased in tumor tissues." (PMID 39440060, 2024).
tumor (continued). "CCR8 and P2RY14 were significantly differentially expressed in tumor tissues compared with normal tissues, while CCR4 was not significantly different." (PMID 33692955, 2021).
hematologic malignancies (1 paper, 2018). "P2RY14 has not been much studied in hematologic malignancies." (PMID 29951132, 2018).
infectious disease (1 paper, 2016). A disorder directly resulting from the presence and activity of a microbial, viral, or parasitic agent in humans. "The other two genes are not known to be specifically involved in infectious diseases, although P2RY14, a G‐protein‐coupled receptor with diverse physiological roles, has been implicated in the modulation of immune function." (PMID 26682570, 2016).
P2RY14 also shares sentences with these, for which no sentence is quoted: diabetes (4 papers); gouty arthritis (4); cancer (3); glioma (3); COVID-19 (2); eosinophilia (2); infection (2); acute myeloid leukemia (1); astrocytoma (1); autonomic neuropathy (1); basophilic leukemia (1); Cerebral ischemia (1); colitis (1); coronary artery disease (1); cystic fibrosis (1); diabetic nephropathy (1); hyperuricemia (1); Insulin resistance (1); ischemia reperfusion injury (1); leukemia (1); neuropathy (1); Pain (1); peritonitis (1); respiratory diseases (1); Sepsis (1); tuberculosis (1); viral infection (1).